IL10 (interleukin 10)
Diseases named in the same sentence as IL10 in open-access papers (continued):
Sharing a sentence is not in itself a finding about the gene and the disease.
Myocardial fibrosis (22 papers, 2015 to 2025). "In vivo and in vitro experiments showed that LIGHT mainly promoted the secretion of cytokines, such as TGF-β1 and IL-10, by inducing macrophage M2 polarisation, thereby increasing the susceptibility to myocardial fibrosis and AF." (PMID 37580750, 2023). "In contrast to WT-EVs, IL-10-KD-EVs incompletely alleviated myocardial fibrosis, inflammation, and capillary loss." (PMID 36203611, 2022). "It decreased myocardial fibrosis and transmurality of the infarct, associated with increased eNOS, p-eNOS, and IL-10 along with decreased expression of TNF-α, IL-6 and iNOS." (PMID 25807532, 2015). "•Azithromycin administration in male albino rats results in significant cardiac damage, including myocardial fibrosis, inflammation, and elevated Interleukin-10 levels." (PMID 39758799, 2025). "IL-10 is generally believed to inhibit myocardial fibrosis through activation of the STAT3 signaling pathway." (PMID 40881586, 2025). "Emerging evidence indicates that exercise intervention can enhance cardiac function by promoting the expression of anti-inflammatory cytokines (e.g., IL-10) and mitigating myocardial fibrosis, oxidative stress, and apoptosis." (PMID 40520009, 2025). "Adoptive transfer of Tregs significantly ameliorated ventricular remodeling and myocardial fibrosis in rats with abdominal aortic constriction-induced HF by suppressing LOX expression via activation of the IL-10/Jak1/STAT3 signaling pathway." (PMID 36911741, 2023). "Masson staining was used to evaluate myocardial fibrosis in the heart tissues of mice in each group, and showed that the degree of myocardial fibrosis in the interstitial and perivascular tissues of mice in the ad-IL-10 group was significantly reduced." (PMID 36794154, 2023). "MI model mice CCR5+ monocytes promote the secretion of anti-inflammatory factor IL-10, mediate Tregs recruitment, inhibit inflammation, and inhibit myocardial fibrosis and cardiac remodeling." (PMID 36911741, 2023). "On the contrary, M2 macrophages secrete interleukin-10 (IL-10), which inhibits cardiomyocyte hypertrophy and myocardial fibrosis." (PMID 33304270, 2020). "It’s also has been hinted that intravenous Tregs can reverse myocardial fibrosis mediated by the secretion of IL-10." (PMID 30057554, 2018). "The mechanism by which immunotherapy with tDCs inhibits the progression of cardiac inflammation and myocardial fibrosis in a mouse model of CCC involves the secretion of IL-10 by tDCs to induce Tregs differentiation and enhance Tregs immunosuppressive function." (PMID 36911741, 2023). "WD-sedentary mice had significantly higher protein levels of TNF-α (a key pro-inflammatory cytokine that contributes to myocardial fibrosis) and lower protein levels of IL-10 (an anti-inflammatory cytokine that is involved in the protection against WD-induced inflammation) than ND-sedentary mice." (PMID 29218015, 2017). "In addition, IL-10 displays pro-fibrotic property in myocardial fibrosis response, which may depend on the balance between anti-inflammatory and pro-fibrotic effects." (PMID 38616256, 2024). "Trichrome staining showed evident myocardial fibrosis in RVH pigs that was significantly blunted by both types of EVs, although IL-10-KD-EVs were less effective than WT-EVs." (PMID 36203611, 2022). "In addition, IL-16 enhances the secretion of inflammatory cytokines such as IFN-γ, IL-10, IL-16, TNF-α, and IL-15 by monocytes and mature macrophages, which promotes the development of myocardial inflammation and thus plays an indirect role in promoting the development of myocardial fibrosis." (PMID 40881586, 2025).
osteosarcoma (22 papers, 2013 to 2025). A usually aggressive malignant bone-forming mesenchymal neoplasm, predominantly affecting adolescents and young adults. "For example, lncRNA ST3Gal6 antisense 1 (ST3Gal6-AS1) promotes metabolism of ceramide in osteosarcoma cells, then promoting the polarization of M2 macrophages, leading to higher level of IL-6 and IL-10 and causing immune escape in osteosarcoma." (PMID 39539540, 2024). "Associations between inflammatory gene polymorphisms (TNF-α 308G/A, TNF-α 238G/A, TNF-β 252A/G, TGF-β1 29T/C, IL-6 174G/C and IL-10 1082A/G) and osteosarcoma (OS) risk remain unclear." (PMID 29228633, 2017). "The increased IL-6 and IL-10 in the microenvironment inhibited the function of T cells, inducing immune evasion in osteosarcoma." (PMID 41502512, 2025). "TAMs in osteosarcoma secrete high levels of immunosuppressive cytokines such as interleukin-10 (IL-10) and transforming growth factor-beta (TGF-β), which inhibit the activation and proliferation of cytotoxic T lymphocytes (CTLs) and NK cells." (PMID 40170852, 2025). "The differentiated macrophages facilitate the migration, invasion, epithelial-mesenchymal transition, and distant lung metastasis capacity of osteosarcoma cells by secreting IL-10, TGF-β, and VEGF." (PMID 40612677, 2025). "For instance, TAM-derived TGF-β and IL-10, both regulated by NF-κB, suppress NK cell cytotoxicity, allowing osteosarcoma cells to evade NK cell-mediated immune surveillance." (PMID 39949765, 2025). "In this work, was highlighted a possible mechanism driven by the action of the anti-IL-10 antibody coupled with mifamurtide which can reverse the resistance of metastatic osteosarcoma to the drug treatment." (PMID 37835437, 2023). "While LPS + IFN-γ–activated M2-like macrophages had low anti-tumor activity, IL-10–polarized M2-like macrophages were able to reduce osteosarcoma cell growth in the presence of the anti-EGFR cetuximab involving antibody-dependent tumor cell phagocytosis." (PMID 24612598, 2014). "Monocyte-derived M1-like and M2-like macrophages were polarized with LPS + IFN-γ, L-MTP-PE +/− IFN-γ or IL-10 and incubated with osteosarcoma cells." (PMID 24612598, 2014). "In addition, four macrophage-related prognostic genes (IL10, VAV1, CD14, and CCL2) had been identified, and the macrophage-related risk model had been validated to be reliable for evaluating prognosis in osteosarcoma." (PMID 34335756, 2021). "Instead, in our experiments, IL-10–polarized M2-like macrophages could be induced to inhibit osteosarcoma cell growth if the tumor cells were coated with the therapeutic anti-EGFR antibody cetuximab." (PMID 24612598, 2014). "Hitherto, IL-10–stimulated M2-like macrophages were unable to inhibit osteosarcoma cell growth." (PMID 24612598, 2014). "Hence, at least for some cell lines, IL-10–stimulated M2-like macrophages have the potential to inhibit osteosarcoma cell growth in an antibody-dependent manner with similar efficacy as antibody-independent inhibition by activated M1-like macrophages." (PMID 24612598, 2014). "The different glutaminolysis networks identified herein in which IL10 + CpG-stimulated MYClow cells use less Gln for oxidative phosphorylation compared with MYChigh cells fits well with previous data demonstrating that MYC-dependent osteosarcoma cells use Gln for cellular respiration." (PMID 29666362, 2018). "In addition, we report that IL-10–polarized M2-like macrophages could exert anti-tumor activity against some osteosarcoma cell lines in an antibody-dependent manner." (PMID 24612598, 2014). "osteosarcoma tumors often exhibit an increased frequency of CD4+CD25+FoxP3+ Tregs, which suppress the activity of CTLs and NK cells through the secretion of IL-10 and TGF-β." (PMID 40170852, 2025). "In TAMs, LPAR6 expression was positively correlated with ADGRE5, IL10, and IL6, which was further validated in the osteosarcoma cohort." (PMID 41502512, 2025).
osteosarcoma (continued). "Next, we investigated the correlation between LPAR6, ADGRE5, IL10, and IL6 in scRNA-seq and the TARGET osteosarcoma cohort." (PMID 41502512, 2025). "For instance, TAMs secrete IL-10 and transforming growth factor-beta (TGF-β), both of which inhibit CTL activation, allowing osteosarcoma cells to escape immune detection." (PMID 39949765, 2025). "In the osteosarcoma TME, Treg further suppress cytotoxic T-cells and NK cells, NF-κB-regulated cytokines like IL-10 and TGF-β playing key roles in enhancing Treg expansion and function, thus contributing to the immunosuppressive environment." (PMID 39949765, 2025). "M2-type macrophages stand out for their pro-tumor tendencies, releasing cytokines such as IL-10 and TGF-β that bolster osteosarcoma’s aggressive trajectory." (PMID 38140058, 2023). "LOC100129620 overexpression promoted IL-10 expression in osteosarcoma cells, and LOC100129620 knockdown inhibited IL-10 expression in osteosarcoma cells." (PMID 34015762, 2021). "Our RT-PCR results showed that IL-10, TGF-β1, VEGFA, and IGF-1 were significantly increased in osteosarcoma tissues." (PMID 32908942, 2020). "Since IL-10–stimulated M2-like macrophages exhibited the highest expression of FcγR in our experiments, we investigated whether these macrophages are able to form cell conjugates with and internalize osteosarcoma cells in an antibody-dependent manner as a potential anti-tumor mechanism." (PMID 24612598, 2014). "However, in the osteosarcoma TME, TAMs predominantly shift towards the M2 phenotype, influenced by NF-κB-regulated factors, including IL-10, transforming growth factor-beta (TGF-β), and macrophage colony-stimulating factor (M-CSF)." (PMID 39949765, 2025). "Furthermore, AGPAT3 knockdown in osteosarcoma cell lines, combined with co-culture experiments, confirmed that LPA regulates TAM-mediated secretion of IL-10 and IL-6 via the LPAR6 signaling pathway." (PMID 41502512, 2025). "To investigate, in vivo, the efficacy of counteracting OS metastatic dissemination by administration of the anti-IL-10 antibody combined with mifamurtide, we performed a lung retention assay in BALB/c mice injected with the highly metastatic K7M2 osteosarcoma murine cells." (PMID 37835437, 2023).
respiratory failure (22 papers, 2014 to 2025). The significant impairment of gas exchange within the lungs resulting in hypoxia, hypercarbia, or both, to the extent that organ tissue perfusion is severely compromised. "A variant in the IL-10 gene, rs3024509, was associated with protection for respiratory failure and for higher CURB-65 and PSI values in this study." (PMID 38143267, 2023). "Our aim was to evaluate the levels of activin A, activin B, FS, IL-6 and IL-10 and their association with the severity of respiratory failure in critically ill H1N1 patients." (PMID 24885241, 2014). "Indeed, it has recently been reported that abrupt cessation of A1AT augmentation therapy for patients with AATD resulted in marked increases in levels of these specific proinflammatory cytokines, a loss of IL-10, and subsequent progression to respiratory failure." (PMID 36831051, 2023). "While the relationship between P/F and LDH is easy to understand since LDH is a marker of the mechanisms leading to regulated necrosis also of lung cells and, therefore, of respiratory failure, the connection with IL-10 is more complex to explain." (PMID 40143288, 2025). "The highest quantity of IL-10 was found in the RSV-infected patients with first-degree respiratory failure and moderate wheezing." (PMID 40430746, 2025). "In our study, elevated IL-6, IL-8, and IL-10 serum levels were correlated with the presence of respiratory failure." (PMID 37969879, 2023). "A longer hospital stay was associated with the presence of respiratory failure and ICU transfer, and serum levels of IL-6, IL-8, and IL-10 were higher in these patients." (PMID 37969879, 2023). "Haplotype combinations in the IL-10 gene were also protective for respiratory failure and highest punctuations in PSI score." (PMID 38143267, 2023). "Third, higher levels of IL-6, IL-8, IL-10, and TNF-α at admission were associated with respiratory failure and disease deterioration." (PMID 34088317, 2021). "Moreover, a positive correlation between the TNF-α/IL-10 ratio and both respiratory failure and disease severity has been documented." (PMID 39061002, 2024). "IL-R1 (rs3917267) and IL-10 (rs3024509) variants were related with respiratory failure (OR = 3.31, p = 0.001 and OR = 0.18, p = 0.003, respectively) as well as several haplotype combinations in NFKBIA, NFKBIZ, IL-R1 and IL-10 (p = 0,02, p = 0,01, p = 0,001, p = 0,03, respectively)." (PMID 38143267, 2023). "Of note, levels of IL-10 were diminished in bronchoalveolar lavage samples of preterm infants with BPD compared to term infants with respiratory failure, indicating a role for insufficient IL-10 expression in the pathogenesis of prolonged lung inflammation and chronic lung injury." (PMID 29234642, 2017). "ROC analysis of variables associated with respiratory failure complicating MPP demonstrated that CRP, IL-10, APTT, D-dimer, and HB were statistically significant predictors of respiratory failure (P < 0.05)." (PMID 39849991, 2025). "Analysis of inflammatory markers and liver and kidney function tests in different groups of children with MPP revealed that those with respiratory failure had significantly elevated levels of white blood cells, neutrophil ratio, PCT, ESR, CRP, IL-6, IL-10, IFN-γ, ALT, AST, and LDH." (PMID 39849991, 2025). "Significant predictors of respiratory failure in children with MPP included CRP (OR ═ 1.013, 95% CI ═ 1.002–1.025), IL-10 (OR ═ 1.034, 95% CI ═ 1.002–1.068), APTT (OR ═ 1.095, 95% CI ═ 1.009–1.187), D-dimer (OR ═ 1.287, 95% CI ═ 1.081–1.532), and HB (OR ═ 0.972, 95% CI ═ 0.941–0.998) (P < 0.05)." (PMID 39849991, 2025).
acute lung injury (21 papers, 2012 to 2026). A condition of lung damage that is characterized by bilateral pulmonary infiltrates (pulmonary edema) rich in neutrophils, and in the absence of clinical heart failure. "In addition, TNF-α and IL-6, which are strongly induced by PFO, are involved in the development of pathological pain as well as fever, and IL-6, IL-8, and IL-10 are reported to cause acute lung injury/ARDS." (PMID 34385995, 2021). "We evaluated the levels of key cytokines, including TNF-α, IL-6, IL-1β, IL-10, IL-17, IL-22, IFN-γ, and TGF-β1, which play central roles in the inflammatory cascade associated with LPS-induced acute lung injury (ALI)." (PMID 41280422, 2025). "Pro-inflammatory cytokines such as TNF-α, IL-6, and IL-1β, coupled with the anti-inflammatory cytokine IL-10, have important functions in the inflammatory process that leads to the advancement of acute lung injury (ALI)." (PMID 38732622, 2024). "The aim of this study is to investigate the role of CXCR3 and IL-10 in lipopolysaccharide (LPS)-induced acute lung injury (ALI)." (PMID 26475448, 2016). "On the other hand, Rg3 was found to decrease the levels of pro-inflammatory mediators (e.g., TNF-α and IL-1β) and increase the production of anti-inflammatory cytokines (e.g., IL-10), resulting in attenuation of damage in lipopolysaccharide-induced acute lung injury in mice." (PMID 31412594, 2019). "In a cecal ligation and puncture (CLP)-induced acute lung injury (ALI) mouse model, luteolin alleviated lung injury, suppressed uncontrolled inflammation, and upregulated levels of interleukin-10 (IL-10) in serum and bronchoalveolar lavage fluid (BALF)." (PMID 41164200, 2025). "IL-10 has been shown to inhibit the production of reactive oxygen species in isolated macrophages and has been suggested to modulate TNF-α mediated, oxidative-stress- induced acute lung injury." (PMID 22978419, 2012). "In a lipopolysaccharide-induced acute lung injury (ALI) rat model, the injection of Ang-1 modified human umbilical cord derived MSCs (hUC-MSCs) could decrease the expression of pro-inflammatory cytokines (e.g., TNF-α, TGF-β1) and increase the expression of anti-inflammatory cytokine IL-10." (PMID 37055866, 2023).
amyloid (21 papers, 2013 to 2025). "Some evidence reported that high expression of IL-10 was associated with low brain amyloid load in humans and with neurogenesis processes and enhanced cognition in animal models of AD." (PMID 40144018, 2025). "For example, in the context of amyloid plaque clearance, it has been shown that IL-10 dampens β-amyloid clearance and IL-10 deficiency permits β-amyloid phagocytosis by microglia." (PMID 34275478, 2021). "Consistent with studies in mice, we found that IL-10 and IL-12/23p40 are jointly associated with the amyloid deposition in the brain, indicating that several factors are involved in this process." (PMID 29070909, 2017). "In earlier studies, we reported that intracerebral expression of the anti-inflammatory cytokines, Interleukin-10 (Il10) and Interleukin-4 (Il4), increased amyloid β (Aβ) burden in TgCRND8 mice, a preclinical model of AD-type amyloidosis." (PMID 40055831, 2025). "The AD transgenic mice fed with Vitamin D showed improved learning and memory abilities, a significant reduction in amyloid plaque load and glial fibrillary acidic protein, and an increase in interleukin-10 (IL-10) in the brain." (PMID 37569241, 2023). "In AD-transgenic (APPSwe/PS1dE9) mice, supplementation with vitamin-D2-enriched mushrooms caused improvement in learning and memory, a reduction in amyloid plaque load and GFAP protein levels and an increase in anti-inflammatory interleukin-10 (IL-10)." (PMID 36831327, 2023). "In fact, IL-33 has proposed to hold anti-inflammatory and protective functions in AD and IL-10, which can be also induced by IL-33 itself, exerts anti-inflammatory actions and was suggested to negatively regulate amyloid pathology in AD-like conditions." (PMID 35515001, 2022). "In this example, they designed a protocol aimed at exploring the effect of the expression of the anti-inflammatory cytokine, interleukin-10 (IL-10), on Aβ pathology in the brains of two mouse models of amyloid pathology (TgCRND8 and Tg2576)." (PMID 36002854, 2022). "Two studies in AD models indicate that IL-10 worsens amyloid-related symptoms in mice and also involve microglial IL-10 in increasing astrocytic production of ApoE, which subsequently loops back to decrease microglial attraction for Aβ." (PMID 36523504, 2022). "Compared with mice on the control diet, VDM-fed wild type and AD transgenic mice displayed improved learning and memory, had significantly reduced amyloid plaque load and glial fibrillary acidic protein, and elevated interleukin-10 in the brain." (PMID 24204618, 2013). "Based on our earlier studies that Il10 and Il4 worsen AD-amyloidosis, we reasoned that blocking the action of these cytokines within the brain could have a protective effect by acting as immune checkpoint inhibitors and preventing Aβ deposition." (PMID 40055831, 2025). "IL-10 deficiency reduced amyloid plaques in APP/PS1 transgenic mice, while genetically-induced overexpression of IL-10 inhibited Aβ phagocytosis and led to increased amyloid burden." (PMID 36358538, 2022). "We observed that FAP 0 patients already exhibited a significant increase in levels of IL-33, IL-1β and IL-10, suggesting that the alterations in immune response might occur before amyloid deposition and symptom appearance." (PMID 31253122, 2019). "Likewise, beneficial regulation of inflammation by subcutaneous injection of Vitamin D3, specifically, up-regulation of IL-10 and down-regulation of IL-1β, was reported in aged F344 rats, devoid of amyloid pathology." (PMID 24204618, 2013). "Moreover, increased IL-10 and IL-13 were significantly associated with moderate to severe neurofibrillary tangle pathology in brain, but not amyloid plaques or Lewy bodies, indicating perhaps that IL-10 and IL-13 might contribute more to tau than amyloid pathology." (PMID 39071802, 2024).